U3 (Small nucleolar RNA U3 )
Synonyms: LOC124903437
Gene: Small nucleolar RNA gene on chromosome 14 (63,651,296 to 63,651,499, reverse strand). Ensembl gene ENSG00000200693.
Gene Ontology:
Biological process: RNA processing
Cellular component: nucleolus
Homologues: Orthologues: chimpanzee U3 (100% identical), macaque U3 (90% identical), rat LOC120095492 (75% identical), rabbit U3 (61% identical). Paralogues in human: SNORD3G (80% identical), U3 (78% identical), SNORD3E (77% identical), U3 (77% identical), SNORD3P1 (76% identical), U3 (76% identical), U3 (75% identical), U3 (74% identical), U3 (73% identical), SNORD3H (73% identical), U3 (72% identical), SNORD3D (72% identical), and 13 more.